IL6 (interleukin 6)
Diseases named in the same sentence as IL6 in open-access papers (continued):
Sharing a sentence is not in itself a finding about the gene and the disease.
renal carcinoma (54 papers, 2003 to 2026). A carcinoma arising from the epithelium of the renal parenchyma or the renal pelvis. "We recently found that IL-6 -174 CC genotype was associated with an increased risk for renal cancer." (PMID 26537097, 2015). "Inhibiting PKC‐mediated phosphorylation pathways in renal cancer cells reduces the release of proinflammatory factors (such as IL‐6), thereby inhibiting tumor progression." (PMID 41244006, 2025). "Epithelial-mesenchymal transition (EMT) was also facilitated in renal carcinoma cells, triggered by compressive forces, induced by increased levels of interleukin-6 (IL-6) via the AKT/GSK-3b/b-catenin pathway activation." (PMID 40171226, 2025). "Therapeutic strategy of IL-6 signaling blockade has been investigated in phase 1 and 2 clinical trials, such as siltuximab in ovarian and renal cancer, with some promising results." (PMID 40255422, 2025). "It would be interesting to evaluate the presence of macrophages in perirenal adipose tissue fragments from healthy patients and patients with renal cancer, as well as the expression of IL-6 in CMs." (PMID 40995093, 2025). "Then, RNA-seq data for CBX7 indicated that CBX7 inactivated the TNF pathway to block tumor growth and downregulated IL6 to sensitize renal cancer cells to TKIs." (PMID 35342353, 2022). "On the other hand, the pre-treatment of simvastatin inhibited phosphorylation of JAK2 and ERK1/2 in renal cancer cells upon IL-6 stimulation." (PMID 35955474, 2022). "Then, we explored the mechanism by which CBX7 regulates the expression of IL6 in renal cancer cells." (PMID 35342353, 2022). "IL-6 is known to be a key factor of tumor-associated inflammation, while co-expression of IL-6 and its receptor in the RCC tissue are associated with a poor prognosis in renal carcinoma patients." (PMID 34603757, 2021). "A monoclonal antibody, CNTO 328 (siltuximab) inhibits JAK/STAT3 signaling and IL-6/IL-6R/gp130 trans-signaling by interfering with the binding of IL-6 and IL-6R and has shown encouraging results in early trials in ovarian and renal cancers." (PMID 33671547, 2021). "To address the effects of NFs on cytokines potentially involved in renal cancer progression, we examined, with ELISA assay, some relevant cytokines, such as IL6, VEGF, CXCL12, and IL1β, in medium with the presence or absence of NF-CM after 72 h." (PMID 31636361, 2020). "IL-6 was found to be secreted by renal cancer cells to act as an autocrine tumor growth factor to induce the transcriptional inflammatory response and promote tumor progression through the JAK-STAT pathway." (PMID 32138303, 2020). "GATA3 overexpression significantly reduced STAT3 phosphorylation and attenuated the migration in both renal cancer cell and IL6-stimulated renal cancer cell." (PMID 31636361, 2020). "Collectively, these results indicate that the IL6-increased STAT3 activation and MMP2 expression in renal cancer cells can be antagonized by concomitant administration of anti-IL6 antibody." (PMID 31636361, 2020). "This suggests a similar amplifier loop in renal cancer, whereby IL-6 is induced by TKIs in RCC cells, consequently up-regulating VEGF expression via AKT and STAT3." (PMID 28903416, 2017). "In vitro, IL-6 protects M1 myeloid leukemia cells against apoptosis induced by cytotoxic drugs, but also renal carcinoma cells (RCC), erythro-leukemic cells and myeloid leukemia cells against the effects of cisplatin." (PMID 19956602, 2009). "The aim of the present study was to examine C-reactive protein, interleukin-6 and interleukin-10 concentrations before and following curative resection of renal cancer." (PMID 17003778, 2006). "At the clinical application level, muscle cell factors are expected to become potential biomarkers for cancer diagnosis and prognosis assessment (such as elevated irisin levels in patients with renal cancer and elevated interleukin-6 levels in patients with bile duct cancer)." (PMID 42094205, 2026).
renal carcinoma (continued). "Attenuated STAT3 activity by si-IL6 sensitized renal cancer cells to doxorubicin." (PMID 36230984, 2022). "Fibroblasts were reported to promote renal cancer cells to secrete IL-6 and phosphorylate STAT3." (PMID 36230984, 2022). "Siltuximab inhibited tumor growth of human renal carcinoma in nude mice by binding to IL-6." (PMID 36209090, 2022). "This study provides the first evidence regarding the effect of normal fibroblasts on renal cancer cells and shows that IL6 can promotes the migration of all four renal cancer cells tested (786-O, 769-P, ACHN, and Caki-1), suggesting an increased ability of metastasis." (PMID 31636361, 2020). "Interestingly, we found that IL6 was enormously increased in all renal cancer cells, while other three cytokines only slightly increased or decreased in one/two kinds of the renal cancer cells." (PMID 31636361, 2020). "By the same token, IL-6 secreted by CD4+ T cells induces renal cancer cell EMT." (PMID 28846080, 2017). "STAT3 has also been reported to be involved in IL-6-induced proliferation of renal cancer cells." (PMID 28878571, 2017). "We suggest that the IL-6 secretion of RCC cells might lead to renal cancer resistance towards TKI therapy, due to the discussed feedback loops." (PMID 28903416, 2017). "EGFR and IL6 are markers of highly invasive tumors, including renal carcinoma." (PMID 25405334, 2014). "In renal carcinoma the majority of cases examined were positive for IL-6 by immunohistochemistry." (PMID 23864954, 2013). "Thus, we hypothesized that canagliflozin might prevent renal cancer from progressing by regressing NLRP3/IL-6/STAT3 activity." (PMID 41068541, 2025). "Commonly studied inflammatory markers such as CRP, IL-6, TNF-α, and procalcitonin (PCT) have all been associated with cancer-related inflammation CRP, for instance, is recognized as a prognostic marker in multiple malignancies, including pancreatic, breast, gastrointestinal, and renal cancers." (PMID 39594709, 2024). "A recent study showed that preserved eggs induced apoptosis in renal cancer cells by up-regulating the expression of the pro-apoptotic factors Bax and IL-10, and down-regulating the expression of the anti-apoptotic factors interleukin-4 (IL-4) and interleukin-6 (IL-6)." (PMID 36832875, 2023). "However, only stage I–II renal cancer patients were employed in the present study; their serum inflammatory factor levels are reported to show no marked difference compared with healthy participants, especial for IL-6." (PMID 35350980, 2022). "Furthermore, it has been demonstrated that renal cancer cells may produce IL-6, which may promote the growth of renal cancer cells in an autocrine manner." (PMID 25013512, 2014). "In renal cancer, the lncRNA SRLR contributes to sorafenib resistance by interacting with NF-κB and promoting IL-6 transcription, which activates the STAT3 pathway." (PMID 39512820, 2024). "Our study shows that SIGIRR downregulation in RCC cells unleashes an inflammatory signaling intrinsic to renal cancer cells that leads to NFKBIZ activation, IL6 induction, MMP1 upregulation, and notably higher levels of PD-L1 and ICAM1 expression." (PMID 35814450, 2022). "IL6 is the downstream gene of TNF signaling 13, and CBX7 contributes to the repression of TNF signaling in renal cancer cells." (PMID 35342353, 2022). "Both TNF-α and its receptors are coexpressed by renal carcinoma cells and, upon binding, the expression of angiogenesis-related genes such as VEGF and IL-6 has been reported." (PMID 19904265, 2009). "Similarly, both Mapk11 and Il6 are cancer-related FDA-approved drug targets and correspond to markers for an unfavorable prognosis for renal cancer." (PMID 39125691, 2024). "Moving deeper into the mechanically driven signaling pathway activation, compression applied in 2D was found to enhance interleukin-6 (IL6)-induced epithelial-to-mesenchymal transition (EMT) and stemness of renal cancer cells through Akt/GSK-3β/β-catenin pathway activation." (PMID 38390314, 2024).
renal carcinoma (continued). "Further studies have shown that IL-6 inhibition induced the efficacy of IFN-α; thus, the addition of tocilizumab may overcome the resistance of renal cancer to IFN-α." (PMID 36230984, 2022). "Taken together, inhibiting the IL6/STAT3 signaling pathway and promoting GATA3 signals may be a therapeutic intervention for the treatment of renal cancer cell metastasis." (PMID 31636361, 2020). "IL6, another STAT3-activating cytokine, has been of much interest and antibodies that neutralize IL6 or block IL6 receptor (R) α are in clinical trials for ovarian, prostate, and renal cancers." (PMID 28186993, 2017). "To date, there is no data on the effects of simvastatin on regulating IL-6-induced JAK2/STAT3 signaling in renal cancer cells." (PMID 23690956, 2013). "Thus, high IL6 levels are an additional phenotypic characteristic of the acute phase reaction for renal cancer patients with high CRP levels, whereas variation in the other acute phase cytokine mediators is not reflected by CRP in renal cancer patients." (PMID 32707675, 2020).
Hypercholesterolemia (53 papers, 2007 to 2025). An increased concentration of cholesterol in the blood. "Four specific baseline variables, one anamnestic (pre-existing hypercholesterolemia) and three laboratory parameters (leucocyte count, IL-6, and fT3), were significantly associated with poor prognosis as independent risk factors." (PMID 38243977, 2024). "Higher IL-6 levels and leucocyte count, lower fT3 concentration, and pre-existing hypercholesterolemia were independent risk factors of poor outcomes in our study population." (PMID 38243977, 2024). "Our findings have suggested four specific baseline variables, one anamnestic (pre-existing hypercholesterolemia) and three laboratory parameters (leucocyte count, IL-6, and fT3), to be significantly associated with poor prognosis as independent risk factors." (PMID 38243977, 2024). "As observed in the HCD group, hypercholesterolemia causes lung inflammation through elevated IL-1β and IL-6 levels, which are physiologically compensated by increased IL-10 levels." (PMID 37082028, 2022). "Moreover, blood cholesterol levels seem to be associated with circulating IL-6 levels, with patients with hypercholesterolemia showed lower IL-6, IL-10 and TNF-α blood concentrations." (PMID 41432903, 2025). "Another experimental study convincingly associates high fat diet-induced hypercholesterolemia in aged ApoE-/- mice not only with elevated plasma levels of IL6, TNF-α, and interferon (IFN)-γ but also higher transcript levels of pro-inflammatory chemokine MCP-1 in brain tissue of these mice." (PMID 34349106, 2021). "Unhealthy dietary habits are high in saturated fat and can promote both acute elevations of pro-inflammatory biomarkers, such as IL-6 and sustained low-grade systemic inflammation, as well as increased BMI, visceral fat mass, and hypercholesterolemia." (PMID 37322363, 2024). "Hypercholesterolemia:Apnoea-(pw9)-central nervous system-(pw27)-↑cortisol-(pw48)-visceral adiposity-(pw21)-↑TNF-α/IL-6-(pw56)-liver-(pw12)-↑LDL-(pw33)-↑oxLDL-(pw51)-↑Hypercholesterolemia." (PMID 35252372, 2022). "In cachexic subjects, sustaining catabolism and inflammation will accelerate the production of TNF-ɑ, IL-6 and IL-1 to block lipoprotein lipase and the L-carnitine-induced fatty acid transfer system, leading to hypertriglyceridemia and hypercholesterolemia." (PMID 34724970, 2021). "Further, the inflammatory markers (CRP, IL-6, and α-TNF) were significantly elevated in the serum of the PG group when compared with the NG group (p < 0.05) confirming the association of hypercholesterolemia with inflammation." (PMID 33202660, 2020). "Frequency of CD4CD38HLADR+ cells was negatively correlated with levels of IL-2 (r = −0.639, p = 0.01) and IL-6 (r = −0.0561, p = 0.03) in patients with hypercholesterolemia." (PMID 29997625, 2018). "Furthermore, αCD3/αCD28-stimulated PBMCs from men with hypercholesterolaemia produced more of IL-1β, and IL-6 compared with cells from normolipidaemic men." (PMID 37901041, 2023). "Furthermore, in vitro and in vivo experimental studies using simvastatin have shown reduction in the expression of proinflammatory cytokines, such as MCP-1, IL-6, and IL-8, in patients with hypercholesterolemia." (PMID 30524484, 2018). "However, Il-2 and IL-6 were negatively correlated with activated CD4+ T cells in patients presenting with hypercholesterolemia." (PMID 29997625, 2018). "However, levels of IL-2 and IL-6 were negatively correlated with activated CD4+ T cells in patients with hypercholesterolemia." (PMID 29997625, 2018). "However, a recent study demonstrated that abrupt termination of statin therapy resulted in a rebound in inflammatory marker levels, such as a rapid increase in interleukin‐6 (IL‐6) levels, in patients with hypercholesterolemia." (PMID 29744151, 2016).
Hypercholesterolemia (continued). "Thus, sEng synergizes with hypercholesterolemia to aggravate endothelial and vessel wall dysfunction in vivo and shows pro-inflammatory activity via nuclear factor-kappa B (NFkB) and interleukin 6 (IL6) in human endothelial cells in vitro." (PMID 32316263, 2020). "Among patients presenting with hypercholesterolemia, the frequency of CD4CD38HLDR+ cells were negatively correlated to IL-6 (r = −0.561, p = 0.03) and to IL-2 levels (r = −0.630, p = 0.01)." (PMID 29997625, 2018). "One study examined the effects of atorvastatin on soluble adhesion molecules, interleukin-6 (IL-6) and brachial artery endothelial-dependent flow mediated dilatation (FMD) in patients with familial (FH) and non-familial hypercholesterolemia (NFH)." (PMID 17374166, 2007). "Hypercholesterolemia, a medical disorder characterized by elevated levels of cholesterol in the bloodstream, has been found to potentially initiate an inflammatory response, resulting in an upregulation of pro-inflammatory cytokines such as TNF-α and IL-6." (PMID 38603728, 2024). "Hypercholesterolemia, being overweight and oxidative stress can induce systemic and vital organ inflammation particularly the heart through overexpression of the pro-inflammatory cytokines which are TNF-α, IL-6, and IL-1 beta." (PMID 33827626, 2021). "Therefore, induction of IL-1β, IL-6, and TNF-α by LDL(-) in macrophages has a link between LDL(-) and inflammation in hypercholesterolemia." (PMID 31534437, 2019). "Chronic inflammation has been reported to increase under hypercholesterolemic conditions and is the mechanism through which hypercholesterolemia induces tissue damage, resulting in the over-production of pro-inflammatory cytokines such as TNF-α, IL-1β, and IL-6 in the HFD-fed mice." (PMID 31920470, 2019). "The aim of the study was to assess the effect of 5α,6α-epoxycholesterol on experimentally induced hypercholesterolemia in rabbits, and the levels of homocysteine (HCY), asymmetric dimethylarginine (ADMA), paraoxonase-1 (PON-1), and inflammatory parameters (IL-6, TNF-α, CRP)." (PMID 29713239, 2018).
sarcoidosis (53 papers, 2015 to 2026). Sarcoidosis is a multisystemic disorder of unknown cause characterized by the formation of immune granulomas in involved organs. "In Slovenian population a promotor polymorphism in the IL-6 gene was found to be a risk factor for sarcoidosis." (PMID 37841263, 2023). "In fact, severe cases of progressive sarcoidosis have been associated with genetic variations in IL-6 coding gene." (PMID 37841263, 2023). "We evaluated MIF in the serum and bronchoalveolar lavage (BAL) fluid of sarcoidosis patients in association with clinical features and cytokines, IL-18, IL-10, IL-6, IFN-γ." (PMID 36207373, 2022). "To understand the regulation of group of cytokines implicated in sarcoidosis, we assessed the levels of IL-6, IL-18, IFN-γ and MIF in the serum samples of sarcoidosis patients (n = 65) and healthy controls (n = 28) via ELISA." (PMID 36207373, 2022). "The increased exercise tolerance, higher HDL levels and reduced AIP values and cytokines (TNF-α and IL-6) in response to exercise training suggested a positive effect of the rehabilitation program on cardiovascular risk in sarcoidosis patients." (PMID 33692469, 2021). "Genetic variations in the genes encoding IL-6 were preferentially upregulated in patients with severe and progressive sarcoidosis thus giving further evidence of the pathogenic role of this proinflammatory cytokine." (PMID 33330556, 2020). "We identified nine biomarkers (IL-1β, IL-6, IL-8, IL-13, VEGF, angiogenin, C4a, RANTES, and MCP-1) that significantly differ in the BAL of patients with HP and sarcoidosis and showed that RANTES and IL-6 are associated with fibrotic outcome." (PMID 40725075, 2025). "The levels of IL-6 were significantly increased in sarcoidosis patients with fibrotic outcome compared to sarcoidosis patients without any fibrotic development (p = 0.03)." (PMID 40725075, 2025). "There are theories regarding a link between sarcoidosis and cytokines, including Th1, IL-2, IL-6, IL-8, IL-12, IL-18, IL-27, interferon gamma, and tumor necrosis factor." (PMID 40259952, 2025). "We revised his underlying diagnosis from cryopyrin-associated periodic syndrome to early-onset sarcoidosis with wild-type NOD2 and established a rationale to use the interleukin-6 (IL-6) receptor blocker tocilizumab (TCZ)." (PMID 38929956, 2024). "Th1 and Th17.1 cells in sarcoidosis-affected skin induced NF-κB–associated inflammatory genes, including LTB, TNF, CCR6, and IL6." (PMID 39225100, 2024). "On the other hand, a patient with sarcoidosis and high urinary IL-6 levels showed a decline in IL-6 concentration in the urine after prednisolone therapy, which also improved renal function." (PMID 37189804, 2023). "When patients with sarcoidosis performed a single bout of treadmill exercise, IL-6 concentrations increased further to concentrations greater than those of the healthy controls." (PMID 36242699, 2023). "In the past, we have shown that in patients suffering from sarcoidosis basal IL-6 concentrations were greater than those of healthy controls due to the chronic inflammatory state of the disease." (PMID 36242699, 2023). "Together, the results of the present study support previous studies that suggest possible central roles for IFN-γ, IL-6, and IL-8 in sarcoidosis." (PMID 35141260, 2022). "IL-6 has been postulated as an important proinflammatory cytokine involved in Th1-mediated immunopathobiology of sarcoidosis." (PMID 36388923, 2022). "With the exception of IL-8, each biomarker in the sarcoidosis panel (eNAMPT, IL-6, ANG-2 IL-1RA, and HBEGF) accurately discriminated between healthy controls and sarcoidosis subjects, with an optimal threshold > 74%." (PMID 36388923, 2022). "The well-established role of IL-6 in the formation of the sarcoid granuloma and evidence that levels of IL-6 correlate with sarcoidosis disease activity and severity make it a unique target for sarcoidosis." (PMID 36314034, 2022).